ACP4 (acid phosphatase 4)
Description:
Protein tyrosine phosphatase that dephosphorylates the receptor tyrosine-protein kinase ERBB4, thereby inhibiting its ligand-induced proteolytic cleavage. Involved in odontogenesis. Regulates odontoblast cell fate via its extracellular catalytic domain by inhibiting proliferation and promoting differentiation (By similarity).
Synonyms: ACPT; AI1J
Tractability: Antibody: UniProt predicts a signal peptide or a membrane-spanning region; the Human Protein Atlas places it where antibodies can reach.
Gene: Protein-coding gene on chromosome 19 (50,790,415 to 50,795,219, forward strand). Ensembl gene ENSG00000142513.
Subcellular location: Membrane
Subcellular location (Human Protein Atlas): Plasma membrane; Microtubules; Nuclear bodies
Gene Ontology:
Molecular function: protein tyrosine phosphatase activity; receptor tyrosine kinase binding; acid phosphatase activity
Biological process: negative regulation of ERBB4 signaling pathway; negative regulation of neuron projection development; negative regulation of protein processing; odontogenesis; peptidyl-tyrosine dephosphorylation involved in inactivation of protein kinase activity; regulation of neuronal synaptic plasticity
Cellular component: lysosome; glutamatergic synapse; membrane; synaptic membrane
Genetic constraint (gnomAD): Loss-of-function variants: 50 observed, 44.79 expected, observed/expected ratio (o/e) 1.12, 90% interval 0.89 to 1.41. The synonymous counts are far from expectation, so gnomAD's model fits this gene poorly and the ratio says little. Missense variants: 594 observed, 547.27 expected, observed/expected ratio (o/e) 1.09, 90% interval 1.01 to 1.16. Synonymous variants: 299 observed, 243.35 expected, observed/expected ratio (o/e) 1.23, 90% interval 1.12 to 1.35.
Homologues: Orthologues: chimpanzee ACP4 (99% identical), dog ACP4 (87% identical), mouse Acp4 (85% identical), pig ACP4 (85% identical), guinea pig ACP4 (82% identical), rat Acp4 (75% identical), tropical clawed frog acp4 (46% identical), Drosophila melanogaster Acph-1 (31% identical), Caenorhabditis elegans pho-5 (29% identical), Drosophila melanogaster CG9449 (27% identical), Caenorhabditis elegans pho-7 (26% identical), Caenorhabditis elegans pho-9 (25% identical), and 11 more. Paralogues in human: ACP2 (43% identical), ACP3 (37% identical), ACP6 (24% identical), PXYLP1 (21% identical), FRA10AC1 (9% identical).
Diseases named in the same sentence as ACP4 in open-access papers:
ACP4 is named in the same sentence as 8 diseases in open-access papers, as found by Europe PMC text mining. Sharing a sentence is not in itself a finding about the gene and the disease. The quoted sentences say what the papers report.
enamel hypoplasia (1 paper, 2020). "Consistently, samples from individuals with enamel hypoplasia exhibited a trend towards higher anti-ACP4 antibody signal by RLBA (p=0.064)." (PMID 32410729, 2020).
enamel-renal syndrome (1 paper, 2021). "While mutations in AMBN and ACP4 cause non-syndromic autosomal recessive hypoplastic AI, mutations in FAM20A cause syndromic autosomal recessive hypoplastic AI (enamel-renal syndrome, OMIM#204690)." (PMID 33652941, 2021).
prostate carcinoma (1 paper, 2022). A carcinoma that arises from epithelial cells of the prostate gland. "ACP4 is an acid phosphatase deregulated in prostate cancer cell line and in testicular cancer tissues." (PMID 36386828, 2022).
ACP4 also shares sentences with these, for which no sentence is quoted: amelogenesis imperfecta (3 papers); diabetes (1); infection (1); testicular cancer (1); tumor (1).